MUC1 (mucin 1, cell surface associated)
Diseases named in the same sentence as MUC1 in open-access papers (continued):
Sharing a sentence is not in itself a finding about the gene and the disease.
colon carcinoma (103 papers, 1993 to 2026). "MUC1 is a transmembrane protein recognized to be aberrantly expressed in a variety of tumors, including pancreatic and colon cancer, and its expression is mostly associated with tumor progression and poor outcome." (PMID 40013338, 2025). "A MUC1 vaccine developed by Dr. Finn’s laboratory was shown to be immunogenic in 43.6% of healthy people at elevated risk for colon cancer and to induce long-term memory B-cell responses." (PMID 40284463, 2025). "Healthy individuals with a history of advanced colonic adenomas and at high risk for colon cancer were enrolled in a clinical trial to evaluate the feasibility of using a MUC1 peptide vaccine to prevent colon cancer." (PMID 39449327, 2024). "MUC1 is significantly expressed in 77% of primary lung malignancies and 70% of human colon tumors, and tumor-associated MUC1 differs from normal cell-expressed MUC1 in terms of both cellular distribution and biochemical characteristics." (PMID 38540735, 2024). "When combined with CEA, CA19-9, and cytokeratin-1 (CK-1), MUC1 emerged as a better biomarker for evaluating the risk of colon cancer than either of the markers alone." (PMID 36980526, 2023). "Mice that received the MUC1 vaccine had a lower risk of developing colitis-associated colon cancer due to a significant increase in anti-MUC1 IgG antibodies and MUC1 antigen-specific T cells." (PMID 38140114, 2023). "A type of MUC1 that is aberrantly overexpressed on the majority of cancer cell surfaces, such as human colon cancer, is commonly mentioned as tumor-associated MUC1 (TA-MUC1) which differs from its normal type in several properties." (PMID 34158526, 2021). "In a previously reported prophylactic vaccine clinical trial, we administered the MUC1 vaccine to patients with a history of advanced colonic adenomas who are at increased long-term risk for colon cancer." (PMID 31275327, 2019). "We have reported that the hypoglycosylated form of MUC1 is over-expressed in colon cancer and its expression is associated with advanced grade of tumors." (PMID 29285251, 2017). "Our mechanistic studies revealed that recombinant TNF-α induced MUC1 gene expression in human colon cancer cells through activation of NF-κB pathway and association of p65 to MUC1 κB promoter sites." (PMID 29285251, 2017). "Firstly, the expression of MUC1 in colon cancer cells induces EMT, which indicates a causative role behind MUC1 expression and its relationship to the severity of colon cancer." (PMID 28717171, 2017). "The results here suggest a possible mechanism, the induction of EMT, behind the previously reported associations between MUC1 expression and poor colon cancer prognosis." (PMID 28717171, 2017). "For example, we previously showed that the synthesis of MUC1-associated sLex in HCT15 colon cancer cells was controlled by methylation of the ST3GAL6 promoter." (PMID 23451223, 2013). "MUC1 is significantly expressed in colon cancer and has been associated with adverse outcomes." (PMID 38540735, 2024). "We recently assessed in two clinical trials in a preventative setting whether immunity induced with a MUC1 peptide vaccine could reduce high colon cancer risk in individuals with a history of premalignant colon adenomas." (PMID 39450169, 2024). "More recently, unglycosylated MUC1 peptide was used in a cancer prevention setting to vaccinate healthy individuals with a history of colonic polyps who were at high risk for developing colon cancer." (PMID 39449327, 2024). "Similarly, a reduced glycosylation of MUC1 increased both susceptibility to colitis and progression to colon cancers." (PMID 33178223, 2020). "We previously reported that in a colon cancer prevention trial of a MUC1 vaccine tested in individuals at increased risk for colon cancer, those who did not mount immune response to the vaccine had higher pre-vaccination levels of circulating MDSC compared to those who did." (PMID 31275327, 2019).
colon carcinoma (continued). "We next asked whether the association between intrinsic Δψm and levels of endogenous mt-associated MUC1 C-ter were unique to subclones derived from SW620 colonic carcinoma cells." (PMID 21966455, 2011). "As MUC1 is expressed on early premalignant lesions as well as cancer, we chose to study immunogenicity, safety and potential efficacy of this vaccine in the preventative setting in individuals with a history of colonic polyps that increases their risk of colon cancer." (PMID 39450169, 2024). "Furthermore, prophylactic immunotherapy targeting MUC1 may be a strategy to strengthen immune surveillance and prevent disease in subjects at hereditary high risk of breast, ovarian and colon cancer." (PMID 24212946, 2011). "Overall, the presence of MUC1 has a profound impact on inflammation onset and severity and colon cancer progression in IBD mouse models." (PMID 40433382, 2025). "In colon cancer, MUC1-Tn has shown to promote regulatory T cell (Treg) expansion and inhibit CD8+ T cell proliferation through APC-MGL interactions." (PMID 41383589, 2025). "The membrane shift and overexpression of MUC1 affect the prognosis of related malignant tumors, like colon cancer." (PMID 39739658, 2024). "MUC-1 is a tumor marker overexpressed in colon cancer, and our data show that MUC-1 positive MVs are statistically significantly increased in CRC patients, even in the early stages of the disease." (PMID 38792021, 2024). "Previously, we vaccinated wild-type mice with MUC1 DNA and challenged them by injection of MUC1-expressing tumor cells in an experimental model of colon carcinoma." (PMID 36980805, 2023). "The number and size of colonic tumors were compared to mice vaccinated with MUC1 DNA alone or BMDCs alone." (PMID 36980805, 2023). "This study highlights the crucial contribution of BMDCs to enhancing antitumor immunity of the MUC1 DNA vaccine and provides supporting preclinical evidence for its tolerance-breaking efficacy in a clinically relevant mouse model of human colon cancer." (PMID 36980805, 2023). "We have previously shown that a MUC1 DNA vaccine can prevent colonic tumors and lung metastasis in C57BL/6 mice." (PMID 36980805, 2023). "When evaluating new biomarkers for colon cancer, MUC1, MUC2, MUC4, MUC5AC, and MUC6 are currently documented in the largest bodies of work regarding their role in the progression from normal colonic tissue to malignancy." (PMID 36900282, 2023). "Mice were vaccinated with MUC1 DNA mixed with autologous bone-marrow-derived dendritic cells (BMDCs), and then colonic tumors were induced by azoxymethane (AOM) injection and oral administration of dextran sulfate sodium (DSS)." (PMID 36980805, 2023). "Multimodal imaging containing SPION, and other metals were constructed to treat MUC-1 expressing colon cancer cell line (HT-29)." (PMID 37650011, 2023). "For example, Muc1 is highly expressed in colon cancer and has been reported as a new target antigen for tumour vaccines." (PMID 36348490, 2022). "In mice, the immune response to MUC1 DNA vaccination was seen to effectively suppress CD4+ T cells in colon cancer cells transfected with MUC1 cDNA." (PMID 34207342, 2021). "The absence of expression of the transmembrane mucin Muc1 is in line with the increased mucus barrier, as it was shown that Muc1 is upregulated under inflammatory conditions, and in diverse cancers, including breast, ovarian, lung, and colon cancer." (PMID 34604725, 2021). "Release of cytochrome c in response to cisplatin was compared between colon cancer cells stably transfected with MUC1 versus empty vector cells." (PMID 33808549, 2021). "Selectin binds to the carbohydrate epitope sLeX (sialyl-Lewis x) and then increases sLeX expression in MUC1-overexpressing colon cancer cells that correlated with metastasis." (PMID 33836774, 2021).
colon carcinoma (continued). "Thirteen patients with PD-L1 and MUC1 positive cancers, including but not limited to lung, pancreatic, ovarian and colon cancer, were enrolled in the trial and received 1 × 109 Muc1-CAR-NK-92 cells/infusion." (PMID 32751977, 2020). "As would be expected from a progressively more immunosuppressive microenvironment, as the disease progressed to colon cancer, fewer individuals in those groups made anti-MUC1 IgG." (PMID 31275327, 2019). "The mucin 1 (MUC1) is a transmembrane protein overexpressed in various tumors, like lung, breast, pancreas, kidney, ovary, and colon tumors." (PMID 31167407, 2019). "SPIONs were not only conjugated with aptamers directed against MUC-1 (marker of colon cancer) but also coated with gold." (PMID 30791358, 2019). "Soluble colon cancer mucins containing mucins MUC1/2 inhibited IL-2 mRNA expression and secretion of CD4+." (PMID 29661177, 2018). "Human colon cancer-derived T84 cells produce mucins (including MUC1), polarize to form tight epithelial barriers, and serve as a useful model of intestinal epithelia." (PMID 28588132, 2017). "The effectiveness of GO-203 in colorectal tumor xenografts can be linked to MUC1 and TIGAR expression in human colon cancers." (PMID 28153010, 2017). "MUC1 is a transmembrane mucin that can promote cancer progression, and its upregulation correlates with a worse prognosis in colon cancer." (PMID 28717171, 2017). "We were interested in the degree of co-expression of EzH2, p-p65 and MUC1 in colon cancer compared to a healthy colon or benign disease." (PMID 29285251, 2017). "Even though distal colonic tumors developed in both WT and MUC1.Tg mice, the incidence of tumors was twice as high in MUC1.Tg mice compared to WT mice." (PMID 29285251, 2017). "We show here that MUC1 induces EMT in colon cancer cells, which likely involved Akt activation, and this was inhibited by treatment with salicylate." (PMID 28717171, 2017). "We examined the effects of overexpression of MUC1 in colon cancer cells, finding that it induced epithelial to mesenchymal transition (EMT), including enhanced migration and invasion, and increased Akt phosphorylation." (PMID 28717171, 2017). "Analysis of human colon cancer tissues microarray showed that hypoglycosylated MUC1, phospho-p65 and EzH2 are co-expressed in colon adenocarcinoma." (PMID 29285251, 2017). "In this study we investigated the effects of overexpressing MUC1 in colon cancer cells with little endogenous expression of MUC1." (PMID 28717171, 2017). "Here, we examined specifically human colon carcinoma tissue microarrays (TMA) by immunohistochemistry for the expression of MUC1 and CIN85 and their potential role in cancer progression and metastasis." (PMID 25675408, 2015). "To examine in vivo the significance of MUC1 expression and its association with CIN85 and Cbl in colon cancer development and progression, we used the AOM/DSS mouse model of colorectal carcinogenesis." (PMID 25675408, 2015). "Co-immunoprecipiation assay revealed that the extracellular domain of tumor form of MUC1 interacts with CIN85 and Cbl molecules in the plasma membrane and cytosol compartment of MUC1-transfected cells and also in colon cancer cells that normally express MUC1." (PMID 25675408, 2015). "A recent study has showed that MUC1 can activate JNK1 to inhibit cisplatin-induced apoptosis in human colon cancer HCT116 cells." (PMID 26057631, 2015). "We therefore investigated the potential association of the tumor form of MUC1 and CIN85 with Cbl in colon cancer cells in vitro and during colon cancer development in vivo." (PMID 25675408, 2015). "Co-immunoprecipitation assay showed that Cbl co-localized both with CIN85 and with MUC1 in a human colon cancer cell line." (PMID 25675408, 2015).
colon carcinoma (continued). "It has also been demonstrated that miR-145 targets MUC1 in metastatic breast cancer, p70S6K1 in colon cancer, c-Myc in non-small cell lung cancer and the transcription factor STAT1 in colon cancer." (PMID 25277192, 2014). "We also showed that MUC1-specific CD4+ T cells played critical roles in the rejection of MUC1-expressing colon carcinoma cells in B6 mice vaccinated with MUC1 cDNA." (PMID 23028615, 2012). "We report that levels of MUC1 are significantly higher in subpopulations of cells with elevated intrinsic Δψm derived from both mammary and colonic carcinoma cell lines." (PMID 21966455, 2011). "To test the effect of MUC1 expression on cancer cell homotypic aggregation, we first compared the adhesive properties of human colon cancer HT29 and HT29-5F7 cells." (PMID 20565834, 2010). "We were unable to show a relationship between DNA methylation status and expression of the MUC4 gene in the LS174T colon cancer cell line, similarly to our results for MUC1." (PMID 19127263, 2009). "We recently reported that MUC1 expression in pancreatic, breast and colon cancer cells is regulated by DNA methylation and histone H3-K9 modification in the 5′ flanking region, also using a MassARRAY compact system." (PMID 19127263, 2009). "For example, a colon cancer specimen was stained by Anti-MUC1* with the most intense staining occurring in the most diseased portions of the specimen." (PMID 18446242, 2008). "In the human colon carcinoma cell line, paracrine stimulation by a soluble factor from human colon connective tissue was involved in inducing the expression of the MUC1 mucin in vitro." (PMID 14760381, 2004). "Additionally, a synergistic anti-tumor effect has been found with the combination of an anti-MUC1-Tn monoclonal antibody (mAb) and a PD-1 inhibitor in colon cancer." (PMID 41383589, 2025). "Transmembrane mucin MUC1 is dysregulated in the progression of colitis to colon cancer." (PMID 38612988, 2024). "MUC1, excessively overexpressed in over 90% of breast tumors and 60% of captured circulating tumor cells (CTCs) from metastatic breast, lung, pancreatic, and colon cancer patients, holds promise as a biomarker for BC CTCs44–46." (PMID 38992001, 2024). "Likewise, increased MUC1 expression was detected in human colon carcinoma HT-29 cells after 6 Gy of X-irradiation." (PMID 36688997, 2023). "Circulating MUC1 has also been reported as an independent predictor of colon cancer." (PMID 36980526, 2023). "Furthermore, in co-immunoprecipitation experiments, the TF epitope on the MUC1 glycoprotein was found as a natural ligand of endogenous GAL-3 in human HT29 colon cancer cells." (PMID 37898403, 2023). "In addition to EpCAM, mucin 1 (MUC1) is overexpressed on CTCs from patients with metastatic lung, pancreatic, and colon cancers." (PMID 37811123, 2023). "Because PNA can enhance tumour cell-endothelial cell adhesion directly by interaction with cell surface MUC1 on tumour cells, MUC1-negative human colon cancer HCT116 and melanoma ACA19-cells were used here to avoid the PNA-MUC1-mediated influence on cancer cell interaction." (PMID 34223877, 2021). "In a recent study, MUC1 has been shown to serve as an adhesion receptor for another gastrointestinal pathogen, enteroaggregative Escherichia coli (EAEC) and knockdown of MUC1 expression in colonic cancer cell line was also associated with reduced EAEC binding." (PMID 31069176, 2019). "As MUC1 is a tumor antigen and oncoprotein that is overexpressed in most tumors, including breast, pancreatic, ovarian, and colon cancers, our result suggests that hypothyroidism may induce abnormal cell metabolism and proliferation of mammary gland cells." (PMID 30332478, 2018).
colon carcinoma (continued). "We completed the first prophylactic cancer vaccine clinical trial based on a non-viral antigen, MUC1, in healthy individuals at-risk for colon cancer." (PMID 27545199, 2016). "MUC1/CIN85/Cbl complex appears to contribute to promotion and progression of colon cancer and thus increased expression of MUC1, CIN85 and Cbl in early stage colon cancer might be predictive of poor prognosis." (PMID 25675408, 2015). "MUC1.Tg mice also showed an increase in the incidence of colon tumors by 40%." (PMID 25675408, 2015). "Interestingly, it has been reported that MUC1 can block death receptor-mediated apoptosis in breast and colonic carcinoma cells." (PMID 24690311, 2014). "The MUC1-specific antibodies have been detected in the sera of breast, pancreatic, and colon carcinoma patients, indicating that MUC1 could induce humoral immune responses." (PMID 19534821, 2009). "In addition, serum Muc1 is a new indicator that may be involved in tumour invasion, which can assist in the early diagnosis of colon cancer." (PMID 36348490, 2022). "Thus, we tested whether expression of MUC1 influences the growth of colon carcinoma cells in MUC1.Tg mice in the orthotopic transplantation model." (PMID 23028615, 2012). "Thus, it is likely that the intrinsic Δψm and associated tumor phenotype are independent of MUC1 over-expression in colonic carcinoma cells." (PMID 21966455, 2011). "Mucin-1 (MUC1) transmembrane protein overexpression supports the development of various tumors such as liver cancer, colon cancer, or RCC." (PMID 40699758, 2025). "Dysregulation of this aberrant form of MUC1 accelerates IBD development and contributes to colon cancer progression by amplifying inflammatory responses in the gut." (PMID 40433382, 2025). "Patients with early-stage colon cancer (T1-T2) had statistically significant higher numbers of total MVs, TF-positive MVs, EMVs, combined EMV/TF MVs, MUC-1-positive MVs, and combined MUC-1/TF MVs." (PMID 38792021, 2024). "This co-localized MUC1/CIN85/CBL complex is suspected to play a significant role in the promotion and progression of colon cancer." (PMID 39130630, 2024). "On the other hand, a complex nanohybrid with optical properties and pH sensitivity was designed using mesoporous silica, CUR-loaded chitosan, and gold with attached Mucin-1 aptamer as a receptor for MUC-1 positive cell lines in breast and colon cancers." (PMID 36839824, 2023). "Treatment of MUC1-expressing colon cancer cells with cisplatin or doxorubicin induced phosphorylation of JNK1 and cJUN, with phosphorylation enhanced by ectopic expression of MUC1." (PMID 33808549, 2021). "MUC1 also activates JNK1 and inhibits cisplatin-induced apoptosis in human colon cancer HCT116 cells." (PMID 34207342, 2021). "In this study we first tested the influence of MUC1 expression on EGFR activation in human breast epithelial and colon cancer cells and assessed the influence of MUC1 intra- and extra-cellular domains on this effect." (PMID 28731466, 2017). "While MUC1 induces EMT in other types of cancers, this is the first demonstration in colon cancer cells, of which the effects of ectopic MUC1 expression have not been extensively examined." (PMID 28717171, 2017). "It shows that stable suppression of the Core 1Gal-transferase (C1GT) by shRNA substantially reduces O-glycosylation in MUC1-positively transfected human colon cancer HCT116 cells and in high MUC1-expressing SW620 cells." (PMID 28725490, 2017). "This study reveals that the expression of cell surface MUC1 is a critical enhancer of EGF-induced EGFR activation in human breast and colon cancer cells." (PMID 28731466, 2017). "Recent studies of colon cancer revealed interactions of DC-SIGN and a few glycoproteins such as CEA, Mac-2BP and MUC1 on the cancer cell surface." (PMID 25402728, 2015). "Here, we analyzed expression of abnormal MUC1 and CIN85 in human colon cancer tissues microarrays (TMA)." (PMID 25675408, 2015).